HDAC6 (histone deacetylase 6)
Diseases named in the same sentence as HDAC6 in open-access papers (continued):
Sharing a sentence is not in itself a finding about the gene and the disease.
acute myeloid leukemia (18 papers, 2013 to 2024). Acute myeloid leukemia (AML) is a group of neoplasms arising from precursor cells committed to the myeloid cell-line differentiation. "For example, HDAC6 inhibition has been linked to increased expression of the pro-apoptotic protein BIM in acute myeloid leukemia cells." (PMID 32013157, 2020). "HDAC6 is overexpressed in multiple cancers cell lines such as ovarian cancer cells, primary oral squamous cells, primary acute myeloid leukemia blasts and myeloblastic cell lines." (PMID 36355493, 2022). "HDAC6 protein degradation is regulated by the Hsp90 chaperone function in turn in K562 cells and primary acute myeloid leukemia (AML)." (PMID 34530730, 2021). "Similar to pan-HDAC inhibitors approved for the treatment of hematological cancers, specific HDAC6 inhibitors showed anti-cancer properties in various cancer types such as multiple myeloma, chronic lymphocytic leukemia, and acute myeloid leukemia." (PMID 32013157, 2020). "Aside from solid tumors, HDAC6 is consistently upregulated in primary acute myeloid leukemia blasts and some myeloblasts, implying an oncogenic role for HDAC6." (PMID 26388610, 2015). "Finally, we investigated combinations of the dual HDAC6/LSD1 inhibitor with cytotoxic agents that are the current standard of care in acute myeloid leukemia (AML) and discovered a significant enhancement of doxorubicin sensitivity." (PMID 36497494, 2022). "Selective inhibition of FLT3, HDAC3 or HDAC6 have been proved useful for the treatment of acute myeloid leukemias, but the benefits of combinations of HDAC3, HDAC6 and FLT3 inhibitors were rarely reported." (PMID 29262547, 2017). "HDAC6 has been reported to be overexpressed in acute lymphoblastic leukemia (ALL), acute myeloid leukemia (AML), breast cancer, CLL, cutaneous T-cell lymphoma (CTCL), hepatocellular carcinoma, oral squamous cell carcinoma, and ovarian and urothelial cancers." (PMID 27886118, 2016). "Previously, HDAC6 inhibition significantly compromised the migration and adhesion of Burkitt's lymphoma cells and reduced VLA4 expression in hematopoietic stem cells and acute myeloid leukemia blast cells." (PMID 31024851, 2019). "It has been reported that acute myeloid leukemia cells lacking in HDAC6 are highly resistant to hydroxamate group HDACIs." (PMID 24023871, 2013).
pancreatic cancer (18 papers, 2012 to 2025). "HDAC6 has also been reported to be highly expressed in human pancreatic cancer tissues and was associated with increased cell migration." (PMID 31142371, 2019). "In this study, we demonstrate that the microtubule-associated deacetylase HDAC6 interacts with the microtubule end binding protein CLIP-170 to stimulate pancreatic cancer cell motility." (PMID 24474193, 2014). "A recent study has shown that ataxin-3 and HDAC6 co-immunoprecipitate and interact, as suggested by a previous surface plasmon resonance study, and overexpression of ataxin-3 promotes the deubiquitination of HDAC6 in pancreatic cancer cells." (PMID 38497605, 2024). "This review focuses on recent studies of HDAC6 in gastrointestinal cancers, including esophageal, gastric, colorectal, liver, and pancreatic cancer, as well as cholangiocarcinoma (CCA)." (PMID 34938729, 2021). "The study of connection between HDAC6 and pancreatic cancer is relatively less than that of other gastrointestinal cancers, but inhibitors of other HDACs have been widely discussed, indicating the possibility of existed connection." (PMID 34938729, 2021). "By scratch wound assays, we found that HDAC6 siRNAs remarkably compromised the ability of pancreatic cancer cells to migrate into the wound area." (PMID 24474193, 2014). "Collectively, these data reveal that the deacetylase activity of HDAC6 is important for its role in promoting pancreatic cancer cell migration." (PMID 24474193, 2014). "The present study reveals that pancreatic cancer samples have higher HDAC6 expression, at both protein and mRNA levels than normal pancreas and adjacent tissues." (PMID 24474193, 2014). "In this study, our data demonstrate that HDAC6 is highly expressed in pancreatic cancer and functions together with CLIP-170 to promote the motility of pancreatic cancer cells, suggesting HDAC6 as a potential target for treating this notorious disease." (PMID 24474193, 2014). "Strikingly, both scratch wound assay and transwell migration assay showed that overexpression of HDAC6 stimulated pancreatic cancer cell migration." (PMID 24474193, 2014). "Evidence for the use of HDAC6 inhibitors to prevent aggresome formation can be found from studies demonstrating that siRNA silencing of HDAC6 abolishes aggresome formation in pancreatic cancer cells." (PMID 24434788, 2014). "We found that HDAC6 mRNA expression was up-regulated in 15 out of 15 samples of pancreatic cancer tissues relative to normal pancreas or adjacent tissues." (PMID 24474193, 2014). "Taken together, these results suggest that HDAC6 acts in concert with CLIP-170 to promote the motility of pancreatic cancer cells." (PMID 24474193, 2014). "In contrast, a significant increase in HDAC6 expression was observed in pancreatic cancer samples; 38.1% of the cancer samples showed low expression and 61.9% had high expression." (PMID 24474193, 2014). "We also performed MTT and SRB assays and flow cytometry to analyze the effects of HDAC6 overexpression on pancreatic cancer cell proliferation and cell cycle progression." (PMID 24474193, 2014). "To corroborate the role of HDAC6 in the motility of pancreatic cancer cells, we studied the effects of its overexpression." (PMID 24474193, 2014). "To investigate the potential role of HDAC6 in the pathogenesis of pancreatic cancer, we examined its expression by immunohistochemistry in normal pancreas, pancreatic cancer, and adjacent tissue samples." (PMID 24474193, 2014). "At present, the mechanisms of how HDAC6 expression is elevated in pancreatic cancer cells are unclear and warrant further investigation." (PMID 24474193, 2014). "The level of HDAC6 mRNA in pancreatic cancer tissues was 16.74-fold and 13.92-fold higher, respectively, than in normal pancreas and adjacent tissues." (PMID 24474193, 2014).
pancreatic cancer (continued). "To test this, we inhibited HDAC6 expression in pancreatic cancer cells by using two different siRNAs, #1 targeting the coding region and #2 targeting the untranslated region." (PMID 24474193, 2014). "However, there is a need for a large-scale study on the direct relationship between HDAC6 expression and clinical data in patients with pancreatic cancer." (PMID 34938729, 2021). "Interestingly, a recent study on pancreatic cancer has reported that MIIP leads to destabilization of HIF-1α by inhibiting the deacetylase activity of HDAC6 and thereby enhancing HIF-1α acetylation." (PMID 34931765, 2021). "Furthermore, regarding pancreatic cancer, HDAC6 inhibition cooperates with the gemcitabine, showing strong potent anticancer effects both in vitro and in vivo, which suggests that targeting HDAC6 is a therapeutic option for pancreatic cancer." (PMID 34938729, 2021). "This study investigated the indirect mechanism through which HDAC6 affects pancreatic cancer." (PMID 34938729, 2021). "Down-regulation of miR-221 expression via increasing HDAC6 function could play an oncogenic role in suppressing autophagy and apoptosis in pancreatic cancer cells." (PMID 32517694, 2020). "Based on prior evidence of efficacy from paclitaxel and HDAC inhibitor combination treatment, the anti-cancer potential of paclitaxel in combination with selective HDAC6 inhibitors was assessed in multiple solid tumor xenograft models, including those of ovarian and pancreatic cancer origins." (PMID 27926524, 2017). "We then investigated whether the interaction with CLIP-170 is involved in the function of HDAC6 in pancreatic cancer cell migration." (PMID 24474193, 2014). "Our study shows that CLIP-170 can be acetylated in cells; however, the level of CLIP-170 acetylation is not affected by the HDAC6 inhibitor tubacin, although the deacetylase activity is necessary for the role of HDAC6 in regulating pancreatic cancer cell motility." (PMID 24474193, 2014). "To gain more insight into the potential functions of HDAC6 in pancreatic cancer, we examined whether it is involved in the motility of pancreatic cancer cells." (PMID 24474193, 2014). "In addition, given that HDAC6 inhibitors are undergoing clinical studies for certain diseases, the data shown in this study suggest an importance for investigating the effectiveness of HDAC6 inhibitors for pancreatic cancer treatment." (PMID 24474193, 2014). "Given the high expression of HDAC6 in pancreatic cancer tissues, we speculated that it might promote the proliferation of pancreatic cancer cells." (PMID 24474193, 2014). "Together, these results suggest that the role of HDAC6 in pancreatic cancer may mainly lie in its metastasis instead of tumor growth." (PMID 24474193, 2014). "To investigate whether the role of HDAC6 in mediating pancreatic cancer cell migration requires its catalytic activity, we treated cells with tubacin, a potent and selective HDAC6 inhibitor, and trichostatin A (TSA), a pan-HDAC inhibitor." (PMID 24474193, 2014). "Thus, other mechanisms must exist responsible for the enhancing effects of HDAC6 on class I HDACs-mediated pancreatic cancer cell growth and survival." (PMID 23251689, 2012). "However, HDAC6 lacks an obvious effect on pancreatic cancer cell proliferation or cell cycle." (PMID 34938729, 2021). "In pancreatic cancer cells, the suppression of HDAC6 could mediate autophagy." (PMID 32517694, 2020). "Our findings indicate that HDAC6 might have value in the diagnosis of pancreatic cancer." (PMID 24474193, 2014). "Second, HDAC6- and SIRT2-mediated deacetylation of KRASMut lysine 104 increases the survival of KRASMut pancreatic cancer cells." (PMID 37779142, 2023). "Further studies reveal that HDAC6 interacts with cytoplasmic linker protein 170 (CLIP-170) and that these two proteins function together to stimulate the migration of pancreatic cancer cells." (PMID 24474193, 2014).
pancreatic cancer (continued). "In this study, we find that histone deacetylase 6 (HDAC6), a member of the class II HDAC family, is highly expressed at both protein and mRNA levels in human pancreatic cancer tissues." (PMID 24474193, 2014). "In addition, it has been reported that histone deacetylase 6 (HDAC6) and SIRT2 deacetylate KRASMut at lysine 104 to increase the survival of KRASMut pancreatic cancer cells." (PMID 37779142, 2023). "No relevant data have been reported for HDAC-4, while high HDAC-6 expression has been emerging as a favorable prognostic factor in terms of survival in invasive breast and pancreatic cancer." (PMID 33799478, 2021). "In agreement with the HDAC6 siRNA results, overexpression of HDAC6 or its catalytically inactive mutant did not significantly affect the proliferation or cell cycle progression of pancreatic cancer cells." (PMID 24474193, 2014). "Together, these results demonstrate that knockdown of HDAC6 expression does not affect the proliferation or cell cycle progression of pancreatic cancer cells." (PMID 24474193, 2014). "We found that siRNA-mediated knockdown of HDAC6 expression did not obviously affect pancreatic cancer cell proliferation." (PMID 24474193, 2014). "Our study also reveals that HDAC6 is involved in the motility but not the proliferation or cell cycle progression of pancreatic cancer cells, which is in agreement with previous findings in other cell types." (PMID 24474193, 2014). "Our results also suggest that class I HDACs play critical roles in pancreatic cancer cell apoptosis and G2 to M phase progression and these effects can be enhanced by class IIa HDACs, but not by HDAC6." (PMID 23251689, 2012). "To determine the roles of these HDACs in pancreatic cancer cell growth and survival, we used three different HDACIs, MGCD0103 (Mocetinostat, a class I-selective HDACI), MC1568 (a class IIa-selective HDACI), and Tubastatin A (a novel HDAC6-specific inhibitor)." (PMID 23251689, 2012). "Another study showed that transfection with miR-221 mimics could inhibit HDAC6 expression in pancreatic cancer cells compared to negative controls." (PMID 32517694, 2020). "HDAC6 does not obviously affect pancreatic cancer cell proliferation or cell cycle progression." (PMID 24474193, 2014).
cervical cancer (16 papers, 2018 to 2025). A primary or metastatic malignant neoplasm involving the cervix. "In the KEGG Viral Carcinogenesis - Reference Pathway, we found that in the cell transformation pathways associated with HPV-related cervical cancer, anal cancer, penile cancer, and head and neck cancer, E7 directly regulates the HDAC6 gene." (PMID 39411320, 2024). "Our study showed that isoflurane exposure caused markedly increase of HDAC6 expression in the cervical cancer cells." (PMID 32833118, 2021). "Therefore, we assembled a set of genes associated with these cervical cancer-related pathways and employed the ssGSEA algorithm to calculate the scores of the HDAC6 and DNMT3B genes in these pathways." (PMID 39411320, 2024). "Therefore, we collected a set of genes related to cervical cancer-associated pathways and used the ssGSEA algorithm to calculate the scores of the HDAC6 and DNMT3B genes in these pathways." (PMID 39411320, 2024). "For example, a study in the model of human cervical cancer indicated that the microtubule-associated histone deacetylase 6 (HDAC6) has different regulatory effects on the microtubule-dependent STIM1 translocation and SOCE activation between cancerous and noncancerous epithelial cells." (PMID 31252656, 2019). "Collectively, depletion of METTL3‐mediated m6A modification leads to abnormally elongated cilia via suppressing HDAC6‐dependent deacetylation of axonemal α‐tubulin, ultimately attenuating cell growth and cervical cancer development." (PMID 39535388, 2025). "For example, YTHDF3 facilitated HDAC6 translation, ultimately attenuating cell growth and cervical cancer development." (PMID 40406242, 2025). "In cervical cancer cells, sevoflurane was found to upregulate histone deacetylase 6 (HDAC6) expression and to promote cell proliferation, migration, and invasion through PI3K/AKT and ERK1/2 signaling pathways." (PMID 40765592, 2025). "Together, these results indicated that HDAC6 plays a role in the METTL3‐regulated malignancy of cervical cancer in vitro." (PMID 39535388, 2025). "Together, these results showed that both METTL3 and HDAC6 promote the progression of cervical cancer in vivo." (PMID 39535388, 2025). "Together, all these results implied the crucial function of the METTL3/HDAC6 axis in the pathogenesis of cervical cancer." (PMID 39535388, 2025). "Further, qRT-PCR and Western blot analyses indicated that both HPV16/18 E7 can upregulate the expression of HDAC6 and DNMT3B, genes associated with HPV infection-related cervical cancer." (PMID 39411320, 2024). "In the HPV-induced cervical cancer pathway, we found that E7 directly interacts with HDAC6, contributing to cell transformation." (PMID 39411320, 2024). "RNA-Seq analysis revealed that overexpression of the HPV16/18 E6/E7 genes upregulated GP6, CD36, HDAC6, ESPL1, and DNMT3B among the differentially expressed genes (DEGs) associated with cervical cancer." (PMID 39411320, 2024). "In cervical cancer, a recent study found that histone deacetylase 6 (HDAC6) is required for STIM1 translocation on microtubules and thus activates Orai1-mediated SOCE." (PMID 36230965, 2022). "miR-22 is down-regulated in cervical cancer and shows inverse correlation with its downstream target HDAC6." (PMID 36076996, 2022). "The present study provides evidence that isoflurane promotes growth of cervical cancer cells, which are mediated by upregulation of HDAC6." (PMID 32833118, 2021). "Previous studies showed that HDAC6 expression was elevated in many cancers including cervical cancer." (PMID 32833118, 2021). "In order to elucidate the correlation between expression of HDAC6 and the role of isoflurane on cervical cancer cells, further study was performed to investigate the knockdown effect of HDAC6 on the proliferative activity of SiHa and Caski cells." (PMID 32833118, 2021). "It is also designed to investigate the role of the isoflurane in the regulation of HDAC6 expression in cervical cancer cells and related pathway." (PMID 32833118, 2021).